LINC-ADAIN (long intergenic non-coding adipose anti-inflammatory)
Synonyms: linc-DMRT2; lnc-DRMT2; TCONS_00015639; formerly LINC01230
Gene: Long non-coding RNA gene on chromosome 9 (1,045,271 to 1,048,641, forward strand). Ensembl gene ENSG00000281769.
Diseases named in the same sentence as LINC-ADAIN in open-access papers:
LINC-ADAIN is named in the same sentence as 5 diseases in open-access papers, as found by Europe PMC text mining. Sharing a sentence is not in itself a finding about the gene and the disease. The quoted sentences say what the papers report.
Obesity (1 paper, 2024). Accumulation of substantial excess body fat. "Subsequent explant of mature implants showed that linc-ADAIN KD had increased adipocyte size and macrophage infiltration compared to control, mimicking hallmark features of adipose tissue remodeling seen in obesity." (PMID 38753486, 2024). "Due to linc-ADAIN’s association with human obesity, we tested whether linc-ADAIN regulated human adipocyte differentiation and lipid storage." (PMID 38753486, 2024). "Future work can address if induction of linc-ADAIN (e.g., through RNA activation) in obese adipose in vivo can provide anti-inflammatory and adipose remodeling effects that may attenuate the cardiometabolic complications of obesity." (PMID 38753486, 2024). "In vivo, linc-ADAIN KD in adipocytes led to adipocyte hypertrophy and larger fat pads as well as increased macrophage infiltration of fat pads implanted into NSG mice—key features of obesity-induced adipose tissue remodeling in obesity and CMD." (PMID 38753486, 2024).
LINC-ADAIN also shares sentences with these, for which no sentence is quoted: endometrial cancer (2 papers); cancer (1); lung adenocarcinoma (1); renal cell carcinoma (1).